IFNGR1 (interferon gamma receptor 1)
Description:
Receptor subunit for interferon gamma/INFG that plays crucial roles in antimicrobial, antiviral, and antitumor responses by activating effector immune cells and enhancing antigen presentation. Associates with transmembrane accessory factor IFNGR2 to form a functional receptor. Upon ligand binding, the intracellular domain of IFNGR1 opens out to allow association of downstream signaling components JAK1 and JAK2. In turn, activated JAK1 phosphorylates IFNGR1 to form a docking site for STAT1. Subsequent phosphorylation of STAT1 leads to dimerization, translocation to the nucleus, and stimulation of target gene transcription. STAT3 can also be activated in a similar manner although activation seems weaker. IFNGR1 intracellular domain phosphorylation also provides a docking site for SOCS1 that regulates the JAK-STAT pathway by competing with STAT1 binding to IFNGR1 (By similarity).
Synonyms: CD119; IFNGR; IMD27A; IMD27B
Tractability: Small molecule: a structure with a bound ligand is known; it has a binding pocket of medium quality. Antibody: UniProt places it where antibodies can reach, with high confidence; its Gene Ontology location is reachable by antibodies, with high confidence; UniProt predicts a signal peptide or a membrane-spanning region; the Human Protein Atlas places it where antibodies can reach. PROTAC: UniProt records ubiquitination sites on it; ubiquitination databases record sites on it; its protein half-life has been measured. Other modalities: an approved drug acts on it.
Gene: Protein-coding gene on chromosome 6 (137,197,483 to 137,219,449, reverse strand). Ensembl gene ENSG00000027697.
Subcellular location: Cell membrane
Subcellular location (Human Protein Atlas): Plasma membrane
Pathways (Reactome):
Immune System: IFNG signaling activates MAPKs; Interferon gamma signaling; Regulation of IFNG signaling
Disease: Potential therapeutics for SARS
Gene Ontology:
Molecular function: protein binding; type II interferon receptor activity; cytokine receptor activity; cytokine binding
Biological process: type II interferon-mediated signaling pathway; type III interferon-mediated signaling pathway; astrocyte activation; cellular response to virus; cytokine-mediated signaling pathway; microglial cell activation; negative regulation of amyloid-beta clearance; positive regulation of amyloid-beta formation; positive regulation of gene expression; positive regulation of tumor necrosis factor production; response to virus; signal transduction; defense response; immune system process
Cellular component: membrane; plasma membrane
Genetic constraint (gnomAD): Loss-of-function variants: 18 observed, 30.29 expected, observed/expected ratio (o/e) 0.59, 90% interval 0.41 to 0.88. The upper end of that interval is the gene's LOEUF score, 0.88, which puts it in group 3 of 6, group 1 being the genes least tolerant of losing a copy. Missense variants: 471 observed, 536.24 expected, observed/expected ratio (o/e) 0.88, 90% interval 0.81 to 0.95. Synonymous variants: 175 observed, 195.11 expected, observed/expected ratio (o/e) 0.9, 90% interval 0.79 to 1.02.
Homologues: Orthologues: chimpanzee IFNGR1 (99% identical), macaque IFNGR1 (95% identical), dog IFNGR1 (58% identical), pig IFNGR1 (58% identical), rabbit IFNGR1 (56% identical), guinea pig IFNGR1 (51% identical), mouse Ifngr1 (50% identical), rat Ifngr1 (48% identical), zebrafish ifnlr1 (13% identical), zebrafish il10ra (13% identical), zebrafish ifngr1l (10% identical), zebrafish crfb15 (10% identical), and 4 more. Paralogues in human: IL20RA (15% identical), IFNLR1 (13% identical), IFNAR2 (13% identical), IL10RB (13% identical), IFNAR1 (12% identical), IL10RA (12% identical), IL20RB (11% identical), IL22RA1 (11% identical), IFNGR2 (10% identical), F3 (10% identical), IL22RA2 (9% identical).
Diseases named in the same sentence as IFNGR1 in open-access papers:
IFNGR1 is named in the same sentence as 193 diseases in open-access papers, as found by Europe PMC text mining. Sharing a sentence is not in itself a finding about the gene and the disease. The quoted sentences say what the papers report.
melanoma (30 papers, 2017 to 2025). A malignant, usually aggressive tumor composed of atypical, neoplastic melanocytes. "High expression of both KLF9 and IFNGR1 was significantly linked to favorable overall survival outcomes in melanoma, as demonstrated by Kaplan–Meier analysis, indicating their possible protective roles similar to WTAP." (PMID 41301778, 2025). "Since the IFN-γ signaling pathway in melanoma cells induces tumor growth arrest and death, mutations of IFNGR1, IFNGR2, JAK1, JAK2, STAT1, and IRF3 lead to insensitivity to anti-tumor IFN-γ activity." (PMID 35432377, 2022). "Notably, loss of IFNGR1 promotes tumour cell proliferation in melanomas and diminishes IFN-Gamma induced apoptosis." (PMID 36075907, 2022). "Whole-exome sequencing of human melanoma tissues and the human melanoma cell line revealed that acquired resistance can result from loss-of-function mutations of IFNGR1, IFNGR2, JAK1, JAK2, STAT1, and IRF3 from the IFN-γ signaling pathway and β2M from antigen presentation pathway." (PMID 35432377, 2022). "Moreover, murine B16 melanoma cells deficient in JAK1 or IFNGR1 grew faster than control B16 cells in response to immune therapy." (PMID 29977240, 2018). "Accordingly, we evaluated the expression patterns of IFNGR1/2 within the melanoma landscape and observed significant expression in almost all clusters." (PMID 41078003, 2025). "A moderate proapoptotic potential of IFN-γ was demonstrated in melanoma cells, while downregulation of IFNGR1 abolished IFN-γ-mediated cell death." (PMID 40108693, 2025). "Supplementary expression analysis revealed that KLF9 and IFNGR1—among the LASSO-selected genes—were consistently downregulated in melanoma samples compared to normal skin across multiple independent datasets, including TCGA and several GEO cohorts." (PMID 41301778, 2025). "To determine the relevance of these residues for the STUB1-mediated regulation of IFNγ-R1 and JAK1, we generated melanoma cell clones deficient in both IFNGR1 and JAK1 (IFNGR1-KO + JAK1-KO) in either a wildtype or STUB1-deficient background." (PMID 35395848, 2022). "Comparative analysis of the IFNγ-R1High and IFNγ-R1Low melanoma populations revealed that cells carrying sgRNAs targeting IFNGR1 were most abundant in the latter population, again confirming the robustness of the screen." (PMID 35395848, 2022). "Here the authors report that melanoma cells with knockout of IFNγR1 show constitutive JAK1/2 activation and that the JAK1/2 inhibitor ruxolitinib can overcome resistance to anti-CTLA-4 therapy." (PMID 36008408, 2022). "This was further confirmed in preclinical experiments using a B16 melanoma model with IFNGR1 knock-down (IFNGR1KD) that showed impaired IFN-γ signaling and reduced sensitivity to anti-CTLA-4 therapy." (PMID 34830176, 2021). "Recent studies have shown that ∼30% of both melanoma and lung carcinomas have at least one mutation in the IFNγ pathway, including JAK1, IFNGR1, or IFNGR2, and resistance to checkpoint inhibitors in patients is associated with JAK1/2 mutations." (PMID 31133614, 2019). "The remaining 23 melanoma cell lines, including the IFNGR1-mutant D22M1 cells, showed minimal cell cycle profile changes when exposed to IFNγ." (PMID 29977240, 2018). "Even if, IFN-γ alone has been tested in clinical trials in melanoma and failed, patients harboring DNA lesions in gene encoding for IFN-γ, as well as mice carrying tumors mutated in IFNGR1, poorly responded to immunotherapy." (PMID 28798748, 2017). "Finally, to explore potential direct effects of IFNγ on B16F10 melanoma cells, we generated Ifngr1-knockout B16F10 cells." (PMID 37996514, 2024).
melanoma (continued). "Using the same RT regimen in the MC38 CRC model, a subsequent study confirmed that host IFN-γ signaling was crucial for RT efficacy, but in contrast to melanoma, tumor IFNGR1 expression was largely dispensable, as transduction with dominant negative IFNGR1 did not affect RT efficacy." (PMID 34830176, 2021). "In addition, deletion of IFNGR1 expression on melanoma cells also abrogated these RT effects, indicating an indispensable role of tumor IFNGR1 signaling in this process." (PMID 34830176, 2021). "Of note, although IFN-I was not required for the induction of resistance, it helped sustain ICB resistance, as additional IFNAR1 ablation on top of IFNGR1 deletion promoted a greater therapeutic response in ICB-resistant melanoma, as compared to IFNGR1 deletion alone." (PMID 34830176, 2021). "Our ligand-receptor-based cell communication analysis demonstrated increased interactions between ETV4-low melanoma cells and T cells, including TNFSF14-LTBR and IFNG-(IFNGR1+IFNGR2) signaling pathways." (PMID 41502516, 2025). "We established an IFNγ-insensitive model of B16F10 melanoma through CRISPR-Cas9 knockout of IFNγR1 (IFNγRKO)." (PMID 39746898, 2025). "In this study, to circumvent the partial attenuation of IFN-γ signaling in IFNγR1KD melanoma and to unequivocally evaluate how tumor IFN-γ signaling affects TILs, we generate the B16 melanoma model with Ifngr1 knocked out by CRISPR-Cas9 (hereafter, IFNγR1KO)." (PMID 36008408, 2022). "In these cells, silencing the expression of Ifngr1 decreased JAK/STAT signaling and made tumors resistant to anti–PD-1 therapy with similar results obtained in melanoma models." (PMID 31133614, 2019). "IFNs can improve ICI responses as loss-of-function mutations in IFN signaling components (i.e., JAK1/2) have been identified in melanoma patients after pembrolizumab treatment relapse, and knockout of IFN pathway mediators such as Jak1, Stat1, Ifngr1 in tumors can weaken ICI treatment efficacy." (PMID 39663510, 2025). "Surprisingly, melanoma cells lacking IFNGR1 exhibited activated JAK1/2, which was a consequence of increased mTOR activity." (PMID 40108693, 2025). "To examine the role of IFN-γ on tumor cells, we challenged C57BL/6 mice with B16 melanoma cells lacking the IFN-γ receptor (Ifngr1–/–)." (PMID 38861331, 2024). "Furthermore, functional studies of human melanoma cell lines and tissues revealed that the IFN-γ-IFNGR1/2-JAK1/JAK2-STAT1/STAT2/STAT3-IRF1 axis promotes PD-L1 expression." (PMID 35432377, 2022). "However, in human melanomas, attenuated IFN-γ signaling as in IFNGR1low SKCMs and in UVMs (lower IFNGR1 expression than SKCMs) is sufficient to induce appreciable effects on TILs, implying that TILs in human melanomas are more sensitive to the dysregulation of tumor IFN-γ signaling." (PMID 36008408, 2022). "Compared to the KO of Ifngr1 in endothelial cells, keratinocytes, myeloid immune cells, and melanocytes, only the mouse model that ablated Ifngr1 in fibroblasts could not develop vitiligo under the melanoma-Treg-induced vitiligo model." (PMID 35950754, 2022).
viral infection (20 papers, 2010 to 2025). "Another interesting note from this experiment is that despite carrying a substantial bacterial load, Tcra−/− and Ifngr1−/− mice are still susceptible to SARS-CoV-2 suggesting that the mere presence of an ongoing BCG infection is insufficient to limit viral infection." (PMID 38086794, 2023). "Severe viral infection predisposition was seen in 3 patients (POLR3A, IFIH1, TLR7XL) and bacterial susceptibility in 3 others (IRF4, IFNGR1, NCSTN)." (PMID 41209815, 2025). "Expression of cell receptors (such as IFNGR1 and CXCR4) was reduced by a viral infection and is associated with suppression of associated signaling pathways and immune function." (PMID 36163484, 2022). "Although in humans RUBV targets a variety of tissues and produces viremia, we found very low or undetectable viral loads in Ifnar1−/− Ifngr1−/− DKO mice, even though these mice are highly susceptible to many viral infections." (PMID 35471083, 2022). "However, IFNG levels were increased only ~three-fold in G+/− and G+/−GR1−/− cell lines upon viral infection, and IFNGR1 levels remained completely unchanged in infected GR1−/− and G+/−GR1−/− cell lines." (PMID 35897807, 2022). "Interestingly, the expression of cell receptors, such as IFNGR1 and CXCR4, was reduced in response to the viral infection and associated with the inhibition of the related signaling pathways and immune functions." (PMID 34944610, 2021). "Our findings for the upregulation of IFNGR1 expression in poly(I:C)-treated rPMCs may confirm that these cells raise their sensitivity to IFN-γ message when exposed to dsRNA-type virus infection." (PMID 32185237, 2020). "The fGR1 mice may also be useful more generally to better define how altering regulation of myeloid cell IFNGR1 affects inflammatory and immune responses in other settings, including viral infections, cancer, and inflammatory/autoimmune diseases." (PMID 28542482, 2017). "There was an elevated expression of IFNAR1 (IFNα/β receptor subunit 1), IFNAR2 (IFNα/β receptor subunit 2), IFNGR1 (IFNγ receptor subunit 1) and IFNGR2 (IFNγ receptor subunit 2) in MIS-C, bacterial infection and KD in comparison with viral infection." (PMID 39300098, 2024). "The absence of IFNG and IFNGR1 further downregulated IFN-γ-responsive transcription factors and cytokines that play a critical role in host immunity against viral infection, events that are independent of the IFN-α/β pathway." (PMID 35897807, 2022).
breast carcinoma (13 papers, 2003 to 2024). "Low expression of IFNGR1 leads to a functional blockade of IFNγ signaling and is associated with breast cancer.Antigen-specific inflammation in cows' mammary gland is characterized by overexpression of interleukins and IFN-γ." (PMID 30271395, 2018). "Blocking IFNGR1 in the breast cancer cells prior to overnight incubation with CM of activated bulk T lymphocytes resulted in a concentration-dependent decrease in passage of the tumor cells through the in vitro BBB." (PMID 39262976, 2024). "The deficiency of Elf5 downregulates the expression of FBXW7 and confers the accumulation of IFNGR1 as a result of the deleted ubiquitination of IFNGR1 in breast cancer cells." (PMID 35814468, 2022). "The IFN-γ signaling pathway therewith is promoted via the elevation of IFNGR1 abundance, which facilitates the propagation of neutrophils as well as the potential proliferation and metastasis of breast cancer." (PMID 35814468, 2022). "Research has suggested that interferon gamma (IFN-γ), an immune potentiating agent, favours activation of mitochondrial-operated apoptotic pathway in breast cancer cell lines by interacting with its receptor, interferon gamma receptor 1 (IFNGR1)." (PMID 28479926, 2017). "The anti-breast cancer effect of I3C might also be through stimulating expression of interferon gamma receptor 1 (IFNγR1) and augmenting the IFNγ response." (PMID 28698459, 2017). "The protein expression levels of TNFAIP6, IFRD1, IFNGR1, and IRF6 were analyzed in 125 breast cancer samples and 18 normal samples by using the UALCAN dataset." (PMID 39765744, 2024). "The heat map tables show the correlation between immune cell infiltrations and TNFAIP6, IFRD1, IFITM2, IFNGR1, IRF6, and NFIL3 in breast cancer." (PMID 39765744, 2024). "Our data show that at a concentration of ∼0.5 μg/ml IFNGR1 mAb, the protein expression levels of both total STAT1 and phosphorylated STAT1 (p-STAT1) decreased to levels comparable to those observed in unstimulated MDA-MB-231 breast cancer cells." (PMID 39262976, 2024). "In order to investigate whether IFN-γ enhanced BBB passage of the MDA-MB-231 breast cancer cells we used neutralizing antibodies to the IFN-γ molecule (anti-hIFN-γ-IgA), and blocked the INF-γ receptor IFNGR1 by using a monoclonal antibody (human IFNGR1/CD119)." (PMID 39262976, 2024). "On the other hand, IFNGR1, IRF6, and NFIL3 were present in the Basal subtype as well as before tumor formation in the cell line of the model, indicating that they could be good markers for Basal subtype breast cancer patients." (PMID 39765744, 2024). "Overall survival analysis showed that TNFAIP6, IFITM2, IFNGR1, and IRF6 expression levels were not significant, whereas IFRD1 (n = 568) indicated a significantly (p < 0.05) increased risk in Luminal A breast cancer patients, along with NFIL3 (n = 219) in Luminal B patients with similar significance." (PMID 39765744, 2024). "The effects of the IFN-γ-blocking antibodies or of the knock-down of IFNGR1 were not a particularity of BT474 cells, similar effects were observed when assaying different HER2-positive cultures from breast cancer PDXs and an additional cell line." (PMID 33623012, 2021). "In breast cancer, high IFN-γ expression and/or lack of IFNγR1 induced strong tumor rejection effects through IFN-γ-dependent or IFN-γ-independent signaling; however, moderate expression of IFN-γ may promote tumor escape and recurrence." (PMID 38216927, 2024).